KCNV2 (potassium voltage-gated channel modifier subfamily V member 2)
Description:
Potassium channel subunit. Modulates channel activity by shifting the threshold and the half-maximal activation to more negative values.
Synonyms: Kv8.2; CDSRR; KV11.1; RCD3B
Tractability: Small molecule: an approved drug acts on it; it belongs to a druggable protein family. Antibody: its Gene Ontology location is reachable by antibodies, with high confidence; UniProt places it where antibodies can reach, with medium confidence; UniProt predicts a signal peptide or a membrane-spanning region.
Gene: Protein-coding gene on chromosome 9 (2,717,510 to 2,730,037, forward strand). Ensembl gene ENSG00000168263.
Subcellular location: Cell membrane
Pathways (Reactome):
Neuronal System: Voltage gated Potassium channels
Gene Ontology:
Molecular function: protein binding; potassium channel regulator activity; monoatomic ion channel activity; voltage-gated potassium channel activity
Biological process: action potential; potassium ion transmembrane transport; monoatomic ion transport; potassium ion transport; protein homooligomerization; transmembrane transport
Cellular component: membrane; plasma membrane; voltage-gated potassium channel complex
Genetic constraint (gnomAD): Loss-of-function variants: 72 observed, 40.69 expected, observed/expected ratio (o/e) 1.77, 90% interval 1.45 to 1.96. The synonymous counts are far from expectation, so gnomAD's model fits this gene poorly and the ratio says little. Missense variants: 1,232 observed, 784.44 expected, observed/expected ratio (o/e) 1.57, 90% interval 1.5 to 1.65. Synonymous variants: 518 observed, 336.17 expected, observed/expected ratio (o/e) 1.54, 90% interval 1.43 to 1.66.
Gene-disease validity (ClinGen):
ClinGen rates the evidence that KCNV2 causes each of these diseases.
inherited retinal dystrophy (autosomal recessive): Definitive. An instance of retinal degeneration that is caused by an inherited modification of the individual's genome.
Homologues: Orthologues: macaque KCNV2 (95% identical), chimpanzee KCNV2 (95% identical), pig KCNV2 (86% identical), guinea pig KCNV2 (83% identical), dog KCNV2 (83% identical), mouse Kcnv2 (83% identical), rat Kcnv2 (83% identical), rabbit KCNV2 (81% identical), tropical clawed frog kcnv2 (62% identical), zebrafish kcnv2a (56% identical), zebrafish kcnv2b (53% identical). Paralogues in human: KCNB2 (31% identical), KCNS1 (30% identical), KCNS3 (30% identical), KCNV1 (30% identical), KCNG1 (28% identical), KCNS2 (28% identical), KCNF1 (27% identical), KCNC3 (27% identical), KCNC4 (27% identical), KCNC2 (26% identical), KCNG4 (26% identical), and 19 more.
Diseases named in the same sentence as KCNV2 in open-access papers:
KCNV2 is named in the same sentence as 35 diseases in open-access papers, as found by Europe PMC text mining. Sharing a sentence is not in itself a finding about the gene and the disease. The quoted sentences say what the papers report.
cone dystrophy (25 papers, 2012 to 2025). An inherited ocular disorder characterized by the loss of cone cells, the photoreceptors responsible for both central and color vision. "Disease-causing variants in KCNV2 cause a monogenic disorder which is classified clinically as cone dystrophy with supernormal rod response (CDSRR)." (PMID 41516321, 2025). "Disease-causing variants in KCNV2 cause cone dystrophy with supernormal rod response (CDSRR), a rare, but severe, inherited retinal dystrophy with an autosomal recessive pattern of inheritance." (PMID 41516321, 2025). "Disease-causing variants in the KCNV2 gene are associated with “cone dystrophy with supernormal rod responses,” a rare autosomal recessive retinal dystrophy." (PMID 38454848, 2024). "Cone dystrophy with supernormal rod response (CDSRR) is an autosomal recessively inherited retinal dystrophy caused by pathogenic mutations in the potassium voltage-gated channel modifier subfamily V member 2 (KCNV2) gene." (PMID 37835784, 2023). "Biallelic pathogenic variants involving the KCNV2 gene have been associated with cone dystrophy with supernormal rod electroretinogram (CDSRR), which is an autosomal recessive disorder." (PMID 35409265, 2022). "Mutations in the KCNV2 gene in humans cause cone dystrophies indicating the essential role of Kv8.2 for normal vision." (PMID 32355203, 2020). "Recessive mutations in KCNV2 have been associated with cone dystrophy with supernormal rod responses (CDSRRs)." (PMID 32967234, 2020). "Mutations in the KCNV2 gene, which encodes the voltage-gated K+ channel protein Kv8.2, cause a distinctive form of cone dystrophy with a supernormal rod response (CDSRR)." (PMID 30820446, 2019). "Notably, mutations in KCNV2 encoding Kv8.2 cause the retinal disorder cone dystrophy with supernormal rod response (CDSRR)." (PMID 40558505, 2025). "In addition, mutations in KCNV2, the gene encoding Kv8.2, cause a retinal disorder in humans termed cone dystrophy with supernormal rod response (CDSRR) or KCNV2 retinopathy." (PMID 40558505, 2025). "KCNV2 is involved in the causation of cone dystrophy with supernormal rod response." (PMID 36836473, 2023). "Finally, mutations in KCNV2, encoding Kv8.2, cause the retinal condition cone dystrophy with supernormal rod response (CDSSR)." (PMID 35876901, 2022). "Likewise, Kcnv2 knockout mice exhibited similar histological changes (reduced ONL, loss of rods, mild impairment of cones) and reduced ERG a-wave as noticed in patients with cone dystrophy with a supernormal rod response (CDSRR) having KCNV2 mutations." (PMID 32967234, 2020). "Kcnv2 was identified during a screening as the disease-causing gene for the retinal condition cone dystrophy with supernormal rod electroretinogram, and ISH was performed on human retinal tissue showing high levels of Kcnv2 expression in the photoreceptor layer." (PMID 24146539, 2013). "Cone dystrophy with a supernormal rod response (CDSRR; OMIM # 610356) is a rare, inherited, retinal disorder related to mutations in the potassium voltage-gated channel modifier subfamily V member 2 (KCNV2) gene." (PMID 39200733, 2024). "The nonsense mutation c.427G > T; p.(Glu143*) in KCNV2 was prevalent UAE and KSA and was associated with CCRD and cone dystrophy with supernormal rod response." (PMID 37127645, 2023). "In this article, we aim to describe the clinical course and associated molecular findings in children with cone dystrophy with supernormal rod response associated with recessive mutations in the KCNV2 gene, which encodes a subunit (Kv8.2) of the voltage-gated potassium channel." (PMID 39200733, 2024). "However, these patients did not develop a cone dystrophy, since mutations in KCNJ10 primarily affect the Müller cell functions, while mutations in KCNV2 lead to disturbed functional integrity of the photoreceptors and probably impair their postreceptoral signaling." (PMID 23077521, 2012).
epilepsy (10 papers, 2013 to 2025). A brain disorder characterized by episodes of abnormally increased neuronal discharge resulting in transient episodes of sensory or motor neurological dysfunction, or psychic dysfunction. "This study aims to investigate the effects of the three potassium channel genes KCNA1, KCNA2, and KCNV2 on increased susceptibility to epilepsy as well as on responsiveness to antiepileptic drugs (AEDs)." (PMID 30441785, 2018). "KCNV2 is known as a marker for severe epilepsy and FAM177B is known to be exclusively expressed in microglia." (PMID 40331981, 2025). "We direct our attention to the possible influence of the KCNA1, KCNA2, and KCNV2 genes on the pathogenesis of epilepsy and responsiveness to treatment involving common drugs." (PMID 30441785, 2018). "Finally, epilepsy classification was correlated with KCNV2/rs10967728 and KCNAB1/rs1551066, KCNJ9/rs2753268 (p-values = 0.033, 0.020, 0.024)." (PMID 40142207, 2025). "In particular Kv8.2 (KCNV2) with epilepsy and Kv9.1 (KCNS1) with chronic pain." (PMID 24062639, 2013). "In conclusion, these studies implicate Kv8.2 (Kcnv2) as an epilepsy gene in rodents and humans." (PMID 24062639, 2013). "In this study, blood samples were collected from 299 healthy controls and 296 Jordanian Arab patients with epilepsy (consisting of 162 patients with good response and 134 patients with poor response), and seven KCNA1, KCNA2, and KCNV2 SNPs." (PMID 30441785, 2018). "Furthermore, the time to remission was correlated with KCNJ10, and KCNV2 and KCNJ9 influenced the classification of epilepsy." (PMID 40142207, 2025). "However, the effects of the KCNA1, KCNA2, and KCNV2 genes on epilepsy development and the effectiveness of AEDs are not yet clear." (PMID 30441785, 2018).
Retinal dystrophy (10 papers, 2012 to 2025). Retinal dystrophy is an abnormality of the retina associated with a hereditary process. "This methodology was applied in a cohort of patients with a form of inherited retinal dystrophy affecting predominantly central vision caused by disease-causing variants in the KCNV2 gene (OMIM *607604)." (PMID 40327004, 2025). "We present a novel method for assessing the eccentric fixation position, as applied in a cohort of patients with KCNV2-associated retinal dystrophy." (PMID 40327004, 2025). "Two patients were subjected to next-generation sequencing via the retinal dystrophies panel and direct sequencing of the KCNV2 genome to identify pathogenic variants." (PMID 39200733, 2024). "The variant in the KCNV2 was found in the Clinvar database with conflicting interpretations of pathogenicity for non-RP disorders (likely benign for dystrophy with supernormal rod response and uncertain significance for Retinal dystrophy)." (PMID 33633220, 2021). "This study describes the genotype and phenotype of six patients with a retinal dystrophy due to changes in the KCNV2 gene." (PMID 23077521, 2012). "Of these patients, seven had monoallelic pathogenic variants in ABCA4, one had biallelic variants of uncertain significance (VUS) in ABCA4, two had monoallelic VUS in ABCA4, and eight harbored VUS in other retinal dystrophy-related genes, including KCNV2, RIMS1, CRB1, CFH, RP1L1, UNC119, and SEMA4A." (PMID 41234456, 2025). "Patients from three families with a phenotype of EoHM and retinal dystrophy had variants in KCNV2 (OFT-00092), MERTK (OFT-00474) and ARL6 (OFT-00407), genes with a phenotype of retinal cone dystrophy in the case of KCNV2 and retinitis pigmentosa in the other two cases." (PMID 35457050, 2022). "Furthermore, 24 families had VUS, two families with variants in genes related to non-syndromic EoHM (SCO2 and ZNF644) and seven families with variants in genes associated with other retinal dystrophies (TRPM1, CACNA1F, KCNV2, RDH5 and MERTK)." (PMID 35457050, 2022). "Evidence from animal models and clinical studies identify KCNV2-retinopathy as a severe early onset retinal dystrophy with slowlyprogressive maculopathy, that might be amenable to future treatments." (PMID 32441199, 2020). "Both genes have been implicated in rare Mendelian disorders: VLDLR (very low-density lipoprotein receptor) – cerebellar ataxia, mental retardation, and disequilibrium syndrome 1, CAMRQ1, MIM#224050 and KCNV2 (voltage-gated potassium channel subunit Kv8.2) – retinal cone dystrophy, RCD3B, MIM#610356." (PMID 24498604, 2013). "Our data suggest that the PRL may not follow a specific pattern in KCNV2-associated retinal dystrophy." (PMID 40327004, 2025). "Thirty (60%) had RPGR-related retinal dystrophy, nine (18%) had ABCA4-Stargardt disease, five (10%) had KCNV2-related retinal dystrophy, three (6%) had RDH12-related retinal dystrophy, two (4%) had Achromatopsia, and one (2%) had Usher syndrome." (PMID 39641965, 2024).
cone-rod dystrophy (4 papers, 2021 to 2023). Inherited retinal dystrophies that belong to the group of pigmentary retinopathies. "KCNV2-associated retinopathy, an autosomal recessive cone-rod dystrophy, has been associated with gene variants in KCNV2, which codes for Kv8.2 and is currently under investigation as a potential target for gene therapy." (PMID 36830640, 2023). "The KCNV2-associated retinopathy is an unusual cone-rod dystrophy characterized by supernormal rod responses and nyctalopia." (PMID 36836473, 2023).
retinal diseases (4 papers, 2019 to 2023). "In the same study, KCNV2-associated retinopathy was identified as the second most common cause (11.3%) of paediatric inherited retinal disease in an Emirati cohort of 71 patients." (PMID 33309813, 2021). "KCNV2-associated retinopathy accounts for 0.7% and 0.25% of families with molecularly confirmed inherited retinal disease in the United Kingdom and Germany, respectively." (PMID 33309813, 2021). "In this respect, KCNV2-retinopathy is similar to other inherited retinal diseases, which show a high degree of interocular symmetry." (PMID 33737031, 2021). "Furthermore, as more is understood about retinal diseases, ERG responses with specific changes in the waveform allow it to act as a non-invasive diagnostic tool, such as for KCNV2 retinopathy and Juvenile X-linked retinoschisis." (PMID 37465364, 2023). "In addition, the presence of intrafamilial variability is a common feature in inherited retinal diseases and has not previously been explored in KCNV2-retinopathy." (PMID 33737031, 2021).
achromatopsia (3 papers, 2021 to 2024). Achromatopsia (ACHM) is a rare autosomal recessive retinal disorder characterized by color blindness, nystagmus, photophobia, and severely reduced visual acuity due to the absence or impairment of cone function. "A later study (and the current report) supported a unique genotype–phenotype correlation related to KCNV2 variants, and PDE6H variants are now considered a rare cause of achromatopsia." (PMID 33309813, 2021).
nyctalopia (3 papers, 2021 to 2023). "To conclude, compound heterozygous variations (c.731G>C and c.280dup) were revealed in the KCNV2 gene of a male with CDSRR, which presented nystagmus, photophobia, dyschromatopsia, and night blindness at an early age, but had uncharacteristic FFERG changes compared to generalized CDSRR patients." (PMID 34535971, 2021).
Arrhythmia (2 papers, 2020 to 2025). Any cardiac rhythm other than the normal sinus rhythm. "Potassium voltage‐gated channel Kcnv2 encodes the ether‐à‐go‐go‐related channel (hERG1) often dysregulated in schizophrenia, cardiac arrhythmia, and tumor proliferation, as well as in normal cell motility involving VIMENTIN (VIM)." (PMID 40674274, 2025).
retinal cone dystrophy type 3B (2 papers, 2013 to 2024). "An unexpected additional finding was a second unique mutation (p.Asn494His) with high scores of predicted pathogenicity in KCNV2, a gene implicated in a rare eye disorder, retinal cone dystrophy type 3B." (PMID 24498604, 2013). "In addition, the mutation is more likely to be pathogenic, and pathogenic variants of the KCNV2 gene can lead to retinal cone dystrophy type 3B." (PMID 39200733, 2024). "The previous nonsense mutation is present in the population database (GnomAD exomes, number of homozygous alleles = 0) at an exceedingly low frequency (8:627,570 alleles, 0.00001275), the variant affecting the KCNV2 gene, which is associated with retinal cone dystrophy type 3B (610,356; AR)." (PMID 39200733, 2024).
breast carcinoma (1 paper, 2017). "Top HBF + BPA-dysregulated genes (ALDH1B1, ASTL, CA7, CPLX4, KCNV2, MAGEE2 and TUBA3E) are associated with poor overall survival in The Cancer Genomic Atlas (TCGA) human breast cancer cohort (n = 1082)." (PMID 28487351, 2017). "To gain clinical significance, using The Cancer Genomic Atlas (TCGA) breast cancer cohort, we dichotomized 1082 breast cancer subjects into two groups based on the expression of the seven genes (ALDH1B1, ASTL, CA7, CPLX4, KCNV2, MAGEE2 and TUBA3E)." (PMID 28487351, 2017). "We took advantage of the publicly available RNA-seq and survival data from TCGA and determined that seven differentially expressed genes (ALDH1B1, ASTL, CA7, CPLX4, KCNV2, MAGEE2 and TUBA3E) could be involved in breast cancer development, especially in Caucasian female patients with ER positivity." (PMID 28487351, 2017). "In the present study, we observed significant change in the methylation status of the promoter region of Car7 and Kcnv2, concomitantly with significant change in their gene expression level, although both genes have never been reported to be breast cancer related in humans." (PMID 28487351, 2017).
colon cancer (1 paper, 2021). "The purpose of this report was to describe the case of a 68-year-old male patient with stage IV colon cancer who exhibited electroretinographic abnormalities that are similar to those of KCNV2 retinopathy." (PMID 33738644, 2021).
juvenile myoclonic epilepsy (1 paper, 2018). "In addition to R7K and M285R, the KCNV2 rs7029012 variant has also been associated with the risk of juvenile myoclonic epilepsy, as it can affect the binding of the acting element by inducing changes in KCNV2 expression." (PMID 30441785, 2018).
lung adenocarcinoma (1 paper, 2023). A carcinoma that arises from the lung and is characterized by the presence of malignant glandular epithelial cells. "Expression of KCNF1 and KCNV2 was significantly increased, while expression of KCNS1 was decreased in lung adenocarcinoma." (PMID 36385523, 2023).
lung carcinoma (1 paper, 2023). "To determine the role of KvS subfamilies in NSCLC, we explored the lung cancer datasets from The Cancer Genome Atlas (TCGA) to inquire expression levels of KCNF1 (Kv5.1), KCNG4 (Kv6.4), KCNV2 (Kv8.2), and KCNS1 (Kv9.1)." (PMID 36385523, 2023).
myopia (1 paper, 2025). "These eyes had a mean refractive error of −4.50 ± 4.49D (range −0.25–−11.13D) and three of these patients (25%; ABCA4, COL2A1, KCNV2) had high myopia." (PMID 41465105, 2025).